CRBN (cereblon)
Diseases named in the same sentence as CRBN in open-access papers (continued):
Sharing a sentence is not in itself a finding about the gene and the disease.
lung fibrosis (1 paper, 2021). "Further detailed studies elucidating the relationship between CRBN and known risk factors for lung fibrosis are needed." (PMID 34002012, 2021). "In this study, we showed that CRBN deficiency may suppress the development of BLM-induced pulmonary fibrosis in mice in vivo and inhibit the TGF-β1-induced activation of lung fibroblasts in vitro by suppressing SMAD3 phosphorylation." (PMID 34002012, 2021). "The objective of this study was to investigate the role of CRBN in bleomycin (BLM)-induced lung fibrosis in mice and TGF-β1-induced differentiation of lung fibroblasts." (PMID 34002012, 2021). "In conclusion, we demonstrated that disruption of the CRBN gene prevented the development of BLM-induced lung fibrosis by suppressing SMAD3 phosphorylation in lung fibroblasts." (PMID 34002012, 2021). "This study provides evidence for the therapeutic potential of targeting CRBN and indicates that CRBN antagonists (inhibitors) may be useful for the treatment of lung fibrosis." (PMID 34002012, 2021). "Taken together, these data suggest that CRBN is a profibrotic regulator and maybe a potential target for treating lung fibrosis." (PMID 34002012, 2021). "To determine whether CRBN mediates lung fibrosis by inactivating AMPKα1, we tested the effect of metformin (a pharmaceutical activator of AMPK) on TGF-β1-induced activation of the SMAD pathway and collagen deposition in CRBN-overexpressing cells." (PMID 34002012, 2021). "Since CRBN negatively regulates AMPK activity, CRBN may be a novel therapeutic target for lung fibrosis." (PMID 34002012, 2021). "Therefore, we evaluated the role of CRBN in bleomycin (BLM)-induced pulmonary fibrosis in mice and in transforming growth factor-beta 1 (TGF-β1)-induced differentiation of human lung fibroblasts." (PMID 34002012, 2021). "Since pulmonary fibrosis was reported to be associated with adenosine monophosphate-activated protein kinase (AMPK) activation, which is negatively regulated by cereblon (CRBN), we aimed to determine whether CRBN is involved in the development of pulmonary fibrosis." (PMID 34002012, 2021). "However, whether CRBN affects lung fibrosis and its underlying mechanism of pathogenesis are not known." (PMID 34002012, 2021).
memory (1 paper, 2024). The activities involved in the mental information processing system that receives (registers), modifies, stores, and retrieves informational stimuli. "Our findings demonstrate that (i) CRBN binds to and inhibits CB1R, (ii) deleting CRBN causes CB1R overactivation, and (iii) this event, in turn, drives CRBN deficiency-associated memory deficits in mice." (PMID 38514794, 2024).
neuroendocrine carcinoma (1 paper, 2025). A malignant neuroendocrine neoplasm composed of cells containing secretory granules that stain positive for NSE and chromogranin. "This study investigated the sensitivity of neuroendocrine cancer (NEC) cells to GSPT1MGDs across a pan-cancer cell line panel, examining the correlation between therapeutic response and cellular characteristics such as CRBN expression and neuroendocrine (NE) marker levels." (PMID 40551250, 2025).
non-syndromic intellectual disability (1 paper, 2021). An intellectual disability that is not part of a larger syndrome.
osteoarthritis (1 paper, 2026). A noninflammatory degenerative joint disease occurring chiefly in older persons, characterized by degeneration of the articular cartilage, hypertrophy of bone at the margins and changes in the synovial membrane. "Previous studies have shown that in osteoarthritis models, CRBN exacerbates disease progression by inhibiting AMPK signaling in chondrocytes, and intra-articular injection of TD-165 mitigates cartilage destruction." (PMID 41424849, 2026).
pancreatic ductal adenocarcinoma (1 paper, 2024). An infiltrating adenocarcinoma that arises from the epithelial cells of the pancreas. "We previously demonstrated that our dTAG molecules known as dTAGV-1 and dTAG-13, which recruit von Hippel-Lindau (VHL) or cereblon (CRBN), respectively, are selective and degrade KRASG12V in several cellular models, including pancreatic ductal adenocarcinoma cell lines." (PMID 39718828, 2024).
plasmacytoma (1 paper, 2014). Plasmacytoma is a localized mass of neoplastic monoclonal plasma cells that represents approximately 5% of all plasma cell neoplasms. "Recently, a novel truncating mutation and R283K point mutation of CRBN were observed in an extramedullary plasmacytoma from a MM patient with clinical resistance to lenalidomide, which is, however, a rare event (4 %) in MM patients." (PMID 24687382, 2014).
renal carcinoma (1 paper, 2019). A carcinoma arising from the epithelium of the renal parenchyma or the renal pelvis. "In contrast, expression of VHL in 786-O cells, a VHL-deficient renal carcinoma cell line, restored TD-158–induced CRBN degradation." (PMID 31873151, 2019).
Salmonella Infections (1 paper, 2019). Infections with bacteria of the genus SALMONELLA. "In terms of functional aspect related to mROS, CRBNKD THP-1 cells exhibited resistance against Salmonella infection, strongly indicating the negative regulation of CRBN on bactericidal activity induced by TLR4 stimulation." (PMID 31620128, 2019).
sarcoma (1 paper, 2019). A usually aggressive malignant neoplasm of the soft tissue or bone. "In addition, we identified CRBN as a promising predictive marker for ARV-825 efficacy across different sarcoma cells and found alternative factors that may impair ARV-825 efficacy, including co-factor expression and proteasomal activity." (PMID 30903020, 2019).
sleep disorder (1 paper, 2024). A change from the patient's baseline sleeping pattern, in the hours slept and/or an alteration/dysfunction in the stages of sleep. "CRBN deficiency in mice alters the response to SD, suggesting CRBN is a potential target for treating sleep disorders and neurodegenerative diseases." (PMID 39349747, 2024). "By illuminating the role of CRBN in regulating sleep–wake behaviors through AMPK, we suggest CRBN as a potential therapeutic target for managing sleep disorders and preventing neurodegeneration." (PMID 39349747, 2024).
synucleinopathies (1 paper, 2024). "In this study, we report CRBN as a measurable marker for the early diagnosis of PD due to its ability to fine-tune the in vitro and in vivo neuroprotective effects of DJ1 and DNAJB6 (DJ6) toward synucleinopathies induced by 1-methyl-4-phenyl-1,2,3,6-tetrahydropyridine (MPTP) and PFFs." (PMID 39443520, 2024).
trypanosomiasis (1 paper, 2021). Infection with protozoa of the genus trypanosoma. "Almost all of these regions and genes were previously related to the trait of interest, while the CRBN gene was to our knowledge presented in the context of trypanosomiasis tolerance for the first time." (PMID 34351956, 2021). "Among these, perhaps the most important finding was the CRBN gene, which, to the best of our knowledge has not been connected with trypanosomiasis before." (PMID 34351956, 2021).
type 1 diabetes (1 paper, 2021). "CRBN levels were found to be reduced, and AMPK levels increased, following exercise of a mouse model of type 1 diabetes, supporting a regulatory role for skeletal muscle CRBN in glucose homeostasis." (PMID 33513781, 2021).
–Lindau disease (1 paper, 2023). "Typically, von Hippel–Lindau disease tumor suppressor (VHL) and Cereblon (CRBN) are the most commonly used endogenous E3 ligases in the PROTAC field." (PMID 37554324, 2023).
cancer (53 papers, 2010 to 2025). A tumor composed of atypical neoplastic, often pleomorphic cells that invade other tissues. "Together these data indicate that CRBN downregulation and/or mutations appear to represent the main mechanism by which MM cells escape the anti-cancer effects of IMiDs in vivo." (PMID 34834536, 2021). "mRNA expression of CRBN varied in different cancer cells, and many somatic mutations in the CRBN gene were found in the database of cancer patients." (PMID 33658395, 2021). "Next, we use the R2: Kaplan Meier Scanner with the TCGA datasets to identify cancer types in which lower CRBN expression was associated with decreased patient survival rates." (PMID 33916291, 2021). "Analysis of genes that are commonly correlated with CRBN expression among KIRC, LUAD, and SKCM samples elucidated the potential CRBN-associated mechanisms of cancer progression." (PMID 33916291, 2021). "Moreover, we validated CSDE1 as a neosubstrate of CRBN, an mRNA and stress-granule associated protein that has been linked to different types of cancer." (PMID 39972349, 2025). "This raises an intriguing question as to whether cancer cells could develop resistance to IMiD-PROTACs by mutating other proteins composing the CRBN E3 ligase." (PMID 36986673, 2023). "However, cancer cells can develop resistant mechanisms to PROTACs through mutation and/or downregulation of E3 ligase machinery corresponding to CRBN or VHL E3 ligase, based on which most PROTACs have been designed." (PMID 36140200, 2022). "Overall, this study revealed the prognostic value of CRBN and its potential associated mechanisms, which may facilitate the development of anti-cancer therapeutic agents." (PMID 33916291, 2021). "Moreover, CRBN-associated pathways were identified through ontology and pathway analysis with co-related genes in multiple types of cancers." (PMID 33916291, 2021). "Thus, STAG1-directed small molecule degraders that engage a suitable human E3 ligase such as VHL or CRBN may provide a promising therapeutic modality for the treatment of STAG2-mutated cancers." (PMID 32467316, 2020). "Moreover, similar results could be seen in cell invasion assay, indicating that CRBN is negatively implicated in cancer progression, presumably through the inhibition of autophagy activation." (PMID 31620128, 2019). "Indeed, it has been reported that IMiDs can impair cereblon, a ubiquitin ligase constitutive in every cell type but crucial for cancer cell survival, causing mis-regulation of developmental signaling molecules and generation of reactive oxygen species, which in turn kill tumor cells." (PMID 29515580, 2018). "NEC cells with high CRBN expression exhibited marked sensitivity to GSPT1 MGDs compared to other cancer types." (PMID 40551250, 2025). "According to clinicaltrials.gov database, of the approximately 25 PROTACs currently in clinical trials, nineteen recruit the cereblon E3 ligase, the vast majority of which are intended for the treatment of cancer." (PMID 40730655, 2025). "In conclusion, this study highlights the therapeutic potential of GSPT1 MGDs in CRBN-high cancers, such as NECs and AML." (PMID 40551250, 2025). "For example, although cereblon expression is high in some cancers, a lower degradation activity of PROTACs is expected due to the lack of a DDB1/CUL4 protein." (PMID 40730655, 2025). "Unlike the universal lethality observed with GSPT1 gene knockout, only cancer cells with a high degree of NE differentiation, characterized by elevated CRBN expression, displayed selective responsiveness to GSPT1 MGDs." (PMID 40551250, 2025). "Taking advantage of this information, several PROTACs resulting from the binding of ML162 derivatives and ligands to cereblon/VHL E3 ligases were synthesized to evaluate the impact of forced GPX4 degradation on cancer cells." (PMID 40730655, 2025).
cancer (continued). "In this study, we identified that the expression level of CRBN, a subunit of the E3 ligase complex, is a critical determinant of cancer cell responsiveness to GSPT1-targeting MGDs." (PMID 40551250, 2025). "We study the cooperative bindingmechanisms of molecular glue degraders, specifically cereblon (CRBN)modulators targeting Ikaros family zinc finger 2 (IKZF2), a transcriptionfactor implicated in cancer immunotherapy." (PMID 40326883, 2025). "The expression levels of CRBN correlate with the sensitivity of anticancer drugs in various cancers." (PMID 41276688, 2025). "This suggested that CRBN(FLT3)-8 selectively targeted and inhibited the growth of cancer cells expressing the FLT3-ITD mutation." (PMID 40793752, 2025). "Although CRBN is often regarded as ubiquitously expressed, our research reveals significant expression differences across various cancer cell lineages that are critical for determining cellular responsiveness to GSPT1 MGDs." (PMID 40551250, 2025). "It acts mainly by binding to Cereblon (CRBN), a member of the E3 ubiquitin ligase complex, which results in the specific targeting of cancer cell survival-associated transcription factors for proteasomal destruction." (PMID 40745380, 2025). "GBD-9 efficiently degraded BTK and GSPT1 proteins with high efficiency (BTK (90%) and GSPT1 (80%) at 50 nM concentration) and inhibited cancer cell growth by recruiting CRBN in a range of DLBCL and AML cell lines." (PMID 40793752, 2025). "As for other chemotherapeutics, chemoresistance against PROTACs has already been reported in clinical trials, in particular for VHL- and CRBN-based agents and cancer cells during long term application." (PMID 39055890, 2024). "In 2010, it was found that thalidomide and its analogs (pomalidomide and lenalidomide) directly bind to CRBN and CRBN-based degraders have been developed to treat human cancers." (PMID 39055890, 2024). "Subsequently, they found that CRBN-based PROTACs were highly potent against other cancer cell lines, but less potent in MOLT-4 cells, possibly due to the low expression of CRBN." (PMID 36733714, 2023). "Lenalidomide, a thalidomide analog, exerts antiproliferative effects in cancer by repressing cereblon (CRBN) and angiogenesis and intensifying the immune response." (PMID 37188182, 2023). "Thalidomide and its analogs are molecular glues (MGs) that lead to targeted ubiquitination and degradation of key cancer proteins via the cereblon (CRBN) E3 ligase." (PMID 38114468, 2023). "CRBN-recruiting PROTAC induced the degradation of TrkC in the Hs578t cancer cell line, with an estimated DC50 in the range of 0.1–1.0 μM." (PMID 36986673, 2023). "Cereblon (CRBN) is an E3 ubiquitin ligase substrate receptor that is involved in cancer cell death, although its regulation is poorly understood." (PMID 34489457, 2021). "The analysis of pathways that are negatively correlated with CRBN expression suggested the potential cancer-promoting mechanisms of CRBN downregulation." (PMID 33916291, 2021). "CRBN mRNA transcription levels were significantly downregulated in 13 out of 16 cancer types compared to normal tissues." (PMID 33916291, 2021). "CRBN-mediated GSPT1 degradation by the next-generation CRBN modulator CC-885 has been shown to have a strong antiproliferative effect in most cancer cell lines with adequate CRBN expression and activity." (PMID 34215850, 2021). "This study systematically assessed CRBN expression and its prognostic value in various cancer types using a variety of bioinformatic analysis tools." (PMID 33916291, 2021). "The anti-cancer effects of lenalidomide are due to its stimulation of cereblon, a component of E3 ubiquitin-ligase, and restoration of the function of immune effector cells." (PMID 34926259, 2021). "In KIRC patients, CRBN mRNA expression was more downregulated in advanced cancer stages characterized by clinicopathologic factors such as grade, stage, and nodal metastasis." (PMID 33916291, 2021).
cancer (continued). "Pathways and ontology terms negatively correlated with CRBN expression were also analyzed using the 42 common genes that were found to be negatively correlated with CRBN in the three cancer types." (PMID 33916291, 2021). "Our findings suggest the value of cereblon as a prognostic marker and potential drug target for different types of cancers from hematopoietic tumors." (PMID 33916291, 2021). "Detailed molecular insight into CRBN–CISM interactions now provides an opportunity to more effectively target previously elusive cancer dependencies, representing a new and powerful tool for the implementation of precision medicine." (PMID 34834536, 2021). "In the present study, we systematically characterized the expression of CRBN in various cancer types by analyzing publicly available expression datasets using web-based mining tools." (PMID 33916291, 2021). "Differential CRBN protein expression in cancer and normal tissues was examined using the UALCAN and human protein atlas websites." (PMID 33916291, 2021). "Among the five cancer types with a significant positive correlation between patient survival and CRBN expression, LUAD, KIRC, and SKCM exhibited the most significant differences in OS between the high and low expression groups." (PMID 33916291, 2021). "CRBN mRNA expression was identified in different cancer types and normal tissue pairs using the TIMER and GENT2 databases." (PMID 33916291, 2021). "Since CRBN was shown to be involved in the anti-cancer effects of thalidomide and its derivatives, researchers next investigated the relevant CRBN substrates." (PMID 32414180, 2020). "To expand the multifunctional roles of CRBN in cancer progression induced by autophagy, we examined the abilities of cancer cell migration and invasion in CRBNKO H1299 and CRBNKO MCF7 cells." (PMID 31620128, 2019). "Meanwhile, our results demonstrate that CRBN negatively regulates cancer migration and invasion through the inhibition of autophagy activation induced by TLR4 stimulation." (PMID 31620128, 2019). "Although the direct evidence of CRBN being capable of affecting cancer progression is insufficient, many reports have suggested that CRBN is closely related to the proliferation and metabolism of normal and tumor cells." (PMID 31620128, 2019). "A potential explanation for this discrepancy is different expression levels and epigenetic modifications controlling the expression of cereblon, Ikaros, and Aiolos, between cancer cell lines and primary cells, as well as differing downstream IL-2-mediated effects following pomalidomide treatment." (PMID 39902962, 2025). "Further supporting this pattern, a positive correlation between SCN scores—a transcriptomic score representing the degree of NE differentiation—and CRBN or DDB1 mRNA expression was also observed in the cancer cell line panels used for CYRS381 sensitivity screening." (PMID 40551250, 2025). "In this study, both cancer types exhibited high CRBN expression and responded strongly to CYRS381." (PMID 40551250, 2025). "Consistent with the observation that GSPT1 degradation kinetics differ depending on cell type, analysis of TCGA pan-cancer datasets revealed that CRBN and DDB1 mRNA levels were positively correlated with NE gene signature scores and inversely correlated with non-NE gene signature scores." (PMID 40551250, 2025). "Screening of our library of CRBN-directed molecular glues against a panel of pediatric cancer cell lines led to the identification of SJ7095 with high cytotoxicity against MOLM-13 cells (IC50 = 71 nM), and potent CRBN-dependent degradation of CK1α, IKZF1 and IKZF3 proteins." (PMID 38228616, 2024). "This suggests that the high effectiveness of IMiD-PROTACs could be achieved in cancers with high expression of CRBN and other proteins of the E3 ligase." (PMID 36986673, 2023). "Therefore, thalidomide and its analogues are now considered as cereblon-modulating drugs, especially for cancer treatment." (PMID 36966238, 2023).